IDO1 (indoleamine 2,3-dioxygenase 1)
Diseases named in the same sentence as IDO1 in open-access papers (continued):
Sharing a sentence is not in itself a finding about the gene and the disease.
tumor (continued). "Tryptophan deprivation by IDO1 has been associated with tumour immune tolerance." (PMID 29156701, 2017). "Blockade of IDO-1 using small molecule inhibitors in combination with immune checkpoint blockade induces prominent antitumor responses in mouse models and reversal of tumor-associated immunosuppression by 1methyl-D-tryptophan appears to be dependent on host IDO1 expression." (PMID 28903363, 2017). "We also find that IDO1 was produced by tumor cells and by tumor-associated interstitial cells that may be CD68+ macrophages or may be other “round” cells observed in these sections, including non-macrophage myeloid derived cells." (PMID 27572319, 2016). "IDO1 expression is known to be immunosuppressive and may enhance tumor immune escape, but it has also been implicated in direct anti-tumor effects." (PMID 21625531, 2011). "In addition, IDO1 is also upregulated in cancer-associated immune cells, such as dendritic cells and macrophages, which promotes immune evasion by depleting tryptophan in the tumor microenvironment, particularly at the immunological synapse." (PMID 39973065, 2025). "Interestingly, tumor overexpression of IDO1 is associated with the amplified assembly of TAMs characterized by high expression of CD206, secretion of elevated levels of TGFβ, and a decrease in pro-inflammatory macrophages expressing NOS2, CD86, and IL-12 within the TME." (PMID 38185636, 2024). "The aberrantly high expression of IDO1 mediated abnormal tryptophan metabolism in cancer cells and promoted the secretion of l-kynurenine (L-kyn)-enriched EVs, with associated high levels of L-kyn in EVs isolated from both the tumor tissues and patient plasma in OC." (PMID 38468343, 2024). "Moreover, restriction of kynurenine-mediated PD-1 induction in tumor-infiltrating T cells upon IDO1 inhibition may even cause PD-1 blockade to be redundant." (PMID 39211039, 2024). "Consistently, our findings indicated that an upregulation of L-kyn in EVs released from IDO1 high tumor cells associated with tryptophan metabolic reprogramming could further result in high levels of L-kyn in EVs derived from tumor tissues and plasma with OC patients." (PMID 38468343, 2024). "Therefore, the biocatalytic activity of IDO1 is closely associated with tumor progression." (PMID 38725031, 2024). "Recently, Sadik and co-workers proposed that IL4I1 expression may also underlie the resistance of patients against IDO1 inhibition, with activation of the AhR presented as their common mechanism of immune response blockade and promotion of tumor cell malignancy." (PMID 36765849, 2023). "We speculate that apart from suppressing IDO1 expression and function, carbidopa serve to inhibit tryptophan entry into tumor cells and tumor-associated immune cells by blocking either the Tryptophan-selective transporter or other amino acid transporters such as SLC6A14 that transport Tryptophan." (PMID 35997090, 2022). "Additionally, IDO-1 has been implicated in tumor vascularization via IFN-G." (PMID 36612271, 2022). "Moreover, tumor-associated IDO1 gene expression strongly correlated with the expression of PD-1, and with increasing level of IFN-γ-responsive gene expression from non-T cell-inflamed to highly T cell-inflamed tumors across multiple human solid tumors from The Cancer Genome Atlas (TCGA)." (PMID 35173722, 2022). "Indomethacin 2,3-double oxygenase 1 (IDO1) is an intracellular enzyme that can cause tryptophan depletion, has been reported to play multiple roles in cancer, including inhibiting T and NK cells, producing active Treg and myeloid-derived suppressor cells and promoting tumor angiogenesis." (PMID 35095898, 2021). "Therefore, a combined targeting of ARG1 and IDO1 using pharmacological compounds could be an effective treatment to constrain tumor-associated immunosuppression improving cancer immunotherapy." (PMID 31447834, 2019).
tumor (continued). "Similar to PD1-targeted immunotherapies, IDO1 agents are expected to have therapeutic potential in subsets across the solid tumor spectrum, and companion biomarkers and identification of susceptible tumor subtypes will likely be essential to IDO1-targeted therapy." (PMID 32082375, 2019). "Therefore, increased IDO1 expression observed in the HPV-associated tumor environment might be induced by IFN-γ-producing NKT cells, resulting in a feed-forward loop of immunosuppression." (PMID 31428574, 2019). "Similarly to PD-L1, IDO1 is overexpressed in different tumors, and is associated with the activation of Foxp3+ Tregs and the down-regulation of cytotoxic cellular immunity in the tumor microenvironment." (PMID 31412566, 2019). "Previous work has suggested an association between cancer, inflammation, and increased IDO1 expression within tumors, suggesting that similar to PD-L1, intratumoral inflammation may lead to adaptive resistance as a mechanism of tumor immune evasion within the tumor microenvironment." (PMID 29805749, 2018). "In addition, IDO1 expression has been associated with the neovascularization of tumor metastasis." (PMID 30186285, 2018). "Collectively, these findings support the hypothesis that the inhibition of IDO1 may increase intratumoral inflammation and increase tumor susceptibility to checkpoint inhibition, making it an ideal target for combining with the inhibition of PD-1 and/or CTLA-4." (PMID 29805749, 2018). "Additionally, IDO1 expression is negatively associated with tumor B-cell infiltration." (PMID 29037255, 2017). "Thus it is likely that tryptophan metabolites, or the administration of IFNα and an IDO1 inhibitor, are in the short term causing their observed effects upon tumor growth by indirect actions upon immune cells, such as altered functionality of intratumoral leukocytes." (PMID 27572319, 2016). "In vitro experiments demonstrated that downregulation of Ido1 in tumor cells was associated with decreased cell proliferation, increased apoptosis, and changed expression of cell cycle regulatory genes, whereas upregulation of Ido1 in the cells had the opposite effects." (PMID 22654951, 2012). "EATL containing more abundant macrophages was enriched in inflammatory response signatures, with upregulation of CD274, CXCL13, and IDO1 transcripts, suggesting an immunosuppressive tumor microenvironment." (PMID 41057685, 2026). "IDO1 expression exhibits significant heterogeneity across glioma subtypes, positively correlates with increasing tumor grade." (PMID 41602107, 2026). "Concurrently, activated NLG919 abolishes the immunosuppressive tumor environment by inhibiting indoleamine 2,3-dioxygenase 1 (IDO-1) and modulating the balance between the essential amino acid L-tryptophan and its metabolite L-kynurenine." (PMID 41427517, 2026). "iDegs inhibited tumor growth in SKOV‐3 tumor‐bearing mice and led to prolonged survival, demonstrating efficacy in in vivo, which promises to inspire novel medicinal chemistry programs aimed at IDO1 in different diseases." (PMID 41310997, 2026). "In vivo experiments corroborate that a high-PA diet significantly elevates tumor growth and IDO1 expression compared to DHA." (PMID 41795590, 2026). "This metabolic imbalance results from upregulated activity of tumor-promoting enzymes (IDO1, TDO2, KMO, KYNU) alongside downregulated protective enzymes(KATs, ACMSD)." (PMID 41602107, 2026). "Western blot analysis demonstrated that ECNM significantly downregulated IDO1 expression in 4T1 tumor cells, indicating its potential to reverse the tumor immune microenvironment." (PMID 41424843, 2026). "Tumour-conditioned medium (TCM) derived from Ido1-OE tumours significantly induced C2C12 myotube atrophy (p < 0.01)." (PMID 42028912, 2026). "iDegs inhibited tumor growth in SKOV‐3 tumor‐bearing mice and led to prolonged survival, which promises to inspire novel medicinal chemistry programs aimed at IDO1 in different diseases." (PMID 41310997, 2026).
tumor (continued). "Artemisinin dimers can target heme-dependent IDO1 for degradation, reducing tumor KYN levels by approximately 75% and synergizing with anti-PD-1 therapy." (PMID 41602107, 2026). "In PDX model mice, tumor IDO1 expression in the PRMT3 inhibitor and radiotherapy groups was found to be lower than in the DMSO and radiotherapy groups." (PMID 41129671, 2026). "High IDO1 and KMO levels were linked to advanced-stage disease, while KAT and KYNU were associated with earlier stages and lower tumor grade." (PMID 42095396, 2026). "Meanwhile, IDO-1 inhibition suppresses tryptophan metabolism-driven immune evasion, thereby reshaping the tumor microenvironment to favor antitumor immunity." (PMID 42256074, 2026). "Co-expression of KYNU seems to play a role in the elimination of immunosuppressive tumor-promoting effects of IDO1/TDO2." (PMID 41282989, 2025). "As the interaction of the well-established oncogene SHP-2 with phosphorylated IDO1 increased in FTC-133 cells in response to the catalytic inhibitors, we explored the functional effects triggered by IDO1/SHP-2 complexes in the tumor cells." (PMID 41262240, 2025). "IDO-1 expression by tumor cells can be part of genetic changes involved in malignant transformation such as loss of Bin-1." (PMID 40475772, 2025). "All these observations highlight the importance of studying and characterizing IDO1 in the context of tumor resistance to targeted therapy and chemotherapy." (PMID 40287406, 2025). "In regard to inflammatory conditions and tumor development, the detection of IDO1 and IFN-γ is crucial for understanding their interplay in immune responses." (PMID 40710094, 2025). "VEGF remodels ECM components during angiogenesis, collaborating with IDO-1 to foster a tumor-promoting niche." (PMID 41019983, 2025). "IDO1, an immune checkpoint-related gene, is positively correlated with poor prognosis and tumor progression and metastasis." (PMID 40083549, 2025). "The value of IDO1 inhibition is not limited to direct anti-tumor effects; it can also improve the immune microenvironment and create conditions for other treatments such as vaccines or cell therapies." (PMID 41451233, 2025). "The use of abatacept or the antibody ipilimumab to block CTLA-4 is now a well-established anti-cancer medication, demonstrating the close relationship between IDO1 activation and autoimmune function as well as tumor formation." (PMID 41035912, 2025). "Mechanistically, HMP1G NPs downregulated tumor cell‐derived IDO1 via the aryl hydrocarbon receptor/signal transducer and activator of transcription 3/interleukin signaling axis to improve kynurenine/tryptophan metabolism and immunosuppression." (PMID 39661740, 2025). "In the microenvironment, the persistence of elevated inflammatory cytokines causes chronic IDO1 expression in antigen-presenting cells (APC) such as macrophages, dendritic cells (DC), and/or tumor cells." (PMID 40332338, 2025). "IDO-1 catalyzes the kynurenine pathway of Trp degradation, which can trigger the onset of tumor immunosuppression." (PMID 40696413, 2025). "Recently, the signaling pathways triggered by the IDO1 protein have also been explored in IDO1-expressing tumor cells." (PMID 41262240, 2025). "Upon reaching the tumor, the liposome cleaved and release IL-15 and IDO1 inhibitor while draining into LNs in a size-dependent manner." (PMID 40159756, 2025). "Enzymes like indoleamine 2,3-dioxygenase (IDO1), which converts tryptophan to kynurenine, are upregulated in tumours." (PMID 40175681, 2025). "There was a significant correlation between IDO-1 positive tumor cells and immune cells; tumor H-Score also showed a significant positive correlation with the amount of tumor immune infiltrate." (PMID 40475772, 2025). "Recent and relevant preclinical studies paradoxically reported tumor-protective mechanisms as a consequence of IDO1 enzymatic inhibition." (PMID 41262240, 2025).
tumor (continued). "The current study, hence, adds details to this established understanding, suggesting that immunomodulation via IL-6 and IDO1 of the tumor microenvironment by MSCs during cisplatin treatment, even at subtoxic doses, is a relevant mechanism to consider." (PMID 40699630, 2025). "In BLCA cells, DAU also impacts the downstream target of HCK/IDO1, which inhibits tumor progression by promoting ferroptosis and ferritinophagy." (PMID 41438182, 2025). "BIN-1, previously characterized as a tumor-suppressor gene, has been shown to act as a transcriptional repressor of the IDO-1 gene through pathways involving signal transducers as well as activator of transcription 1 (STAT1) and NF-κB." (PMID 39859561, 2025). "None of the analyzed variables (age, sex, histology, stage, EGFR, KRAS) were found to display a significant correlation with IDO-1 positivity in tumor and immune cells." (PMID 40475772, 2025). "Both PD-L1 and IDO-1 overexpression are induced by TH1/IFNγ signaling as occurs at the tumor-infiltrating lymphocytes (TILs) level and are significantly higher in the tumor compartment than in stromal cells." (PMID 40475772, 2025). "We also demonstrate higher expression of immunoregulatory molecules (PD-L1, PD-L2, B7-H3, B7-H4, IDO1, and VISTA) among tumor-associated macrophages." (PMID 40459946, 2025). "By intervening in key metabolic nodes, such as inhibiting LDHA or indole 2,3-dioxygenase (IDO1), it is possible to boost the anti-tumor activity of immune cells." (PMID 41164182, 2025). "These metabolic adaptations sustain tumor survival and contribute to immune suppression, as seen in the Wnt5a-indoleamine 2,3-dioxygenase 1 (IDO1) axis, which fosters regulatory T-cell expansion and an immunosuppressive microenvironment." (PMID 40917745, 2025). "In our study, the anti-tumor activity of IDO1 inhibitors RY103 and 1-L-MT were tested in C1498 AML bearing mice." (PMID 40234305, 2025). "In tumor‐draining lymph nodes (TDLN), antigen‐presenting cells (APCs, such as dendritic cells) inherently expressing IDO1 induce iTregs, suppress T effector cells (Teffs), and result in systemic tumor immune suppression." (PMID 40103267, 2025). "While challenges remain, the continued exploration of IDO1 inhibition reflects its compelling biological rationale and the need for innovative approaches to overcome tumor immune evasion in cancer immunotherapy." (PMID 40894232, 2025). "HPV-positive tumor cells had increased IDO1, HLA-DR, and Ki67 positivity, whereas HPV-negative tumor cells were more frequently CD44 positive, reflecting a more stem-like phenotype." (PMID 41254766, 2025). "The IFN-γ-TOPK-eIF4F-STAT1-PD-L1/IDO1 axis as a crucial regulator of the tumor immunometabolic microenvironment and provide novel insights into the combination of targeted therapy and immunotherapy for GC treatment." (PMID 41417572, 2025). "Blocking IDO1 activity can reduce tumor proliferation and enhance the efficacy of radiotherapy, immunotherapy, and chemotherapy." (PMID 40332338, 2025). "Ido1 in turn is known to facilitate tumor immune escape by suppressing T cell activity and promoting Treg expansion." (PMID 40526430, 2025). "Indoleamine 2,3-dioxygenase 1 (IDO1), the rate-limiting enzyme in tryptophan catabolism, is overexpressed by tumor cells and immunosuppressive cells in response to inflammatory signals." (PMID 41281945, 2025). "Despite significant downregulation of target antigen occurred in tumor tissue in five out of seven patients after surgery, upregulation of PD-L1 and IDO1 expression was concurrently observed in the TME." (PMID 40969260, 2025). "The metabolic effects of IDO1 extend beyond immune evasion, influencing key nutrient utilization pathways that sustain tumor cell survival." (PMID 40917745, 2025). "Because IDO1 supports immune tolerance but also facilitates tumor progression, research has focused on developing IDO inhibitors." (PMID 41035912, 2025).
tumor (continued). "Meanwhile, the top three genes that are least correlated with KLF4 and associated with a tumor inhibitory effect in several tumors were BTLA, IDO1, and LAG3." (PMID 40299916, 2025). "Epacadostat can interfere with the abnormal metabolism of Trp in tumor cells by competing for binding to the enzymatically active catalytic structural domain of IDO1, thereby inhibiting tumor growth." (PMID 39857808, 2025). "In the tumor microenvironment, IDO1 was suggested to contribute to immunosuppression by depleting tryptophan, an essential amino acid for T cell function, and by increasing kynurenine levels." (PMID 40565041, 2025). "The immunosuppressive role of IDO1 within the Kyn-AhR axis in GBM tumour environment has been extensively studied in the past decade." (PMID 40471422, 2025). "The released Mn2+ catalyzed the production of abundant reactive oxygen species and nitric oxide from hydrogen peroxide and GSNO, and the generated nitric oxide, synergistically with 1‐MT, inhibited the accumulation of kynurenine mediated by IDO1 in the tumor." (PMID 39661740, 2025). "A comprehensive analysis indicated that, in comparison with normal tissue, IDO1 resulted highly expressed in more than twenty tumor types including BC." (PMID 40287406, 2025). "Indoleamine 2,3-dioxygenase 1 (IDO-1), an enzyme overexpressed in tumor tissues, converts tryptophan to kynurenine, depleting tryptophan in the tumor microenvironment and suppressing T cell function, thus facilitating tumor immune evasion." (PMID 39861694, 2025). "The de novo pathway has been studied extensively in the context of cancer, as IDO1 is highly expressed by tumour cells across various types of cancer." (PMID 40751253, 2025). "IDO1's impact on tumor growth and apoptosis has strengthened the case for using its inhibitors in cancer therapy." (PMID 40103267, 2025). "While clinical studies indicate that IDO1 inhibitors alone have limited anti-tumor effects, their combination with other immunotherapies, such as checkpoint inhibitors, demonstrates synergistic potential to improve survival rates." (PMID 40287406, 2025). "Preclinical evidence suggests that PROTAC-mediated IDO1 removal enhances checkpoint inhibitor efficacy by reshaping the tumor immune microenvironment." (PMID 40894232, 2025). "IDO1's pro‐angiogenic activity in both tumor and non‐tumor tissues helps create a favorable microenvironment for tumor initiation, later promoting tumor growth and metastasis." (PMID 40103267, 2025). "Preclinical models show that combining a low-tryptophan diet with IDO1 inhibition produces synergistic anti-tumor effects by limiting Trp availability and suppressing KYN-driven immune evasion." (PMID 40666095, 2025). "IDO1, which is widely expressed by tumor cells and APCs, controls T cell activity by reducing tryptophan and building up kynurenine metabolites in the microenvironment." (PMID 41476956, 2025). "Inhibition or deficiency of IDO1 enhanced NK cell anti-tumor activity against NSCLC in vitro, and a combination of an IDO1 inhibitor with NK cells was more efficacious in tumor killing than either alone." (PMID 40849493, 2025). "Among the various immunoregulatory pathways, the indoleamine 2,3-dioxygenase 1 (IDO1)-mediated kynurenine pathway has emerged as a central player in tumor immune evasion." (PMID 40894232, 2025). "Therapeutic targeting of this metabolic–immune checkpoint, particularly through IDO1 inhibition or Trp restriction, represents a compelling anti‐tumour strategy." (PMID 41275427, 2025). "The functions of IDO1 are likely related to its role in modulating immune responses and the tumor microenvironment, providing strong evidence that IDO1 is a therapeutic target for TNBC." (PMID 40217479, 2025). "In conclusion, IDO1 plays a crucial role in immunosuppression and tumor immune evasion through the regulation of tryptophan metabolism, making it a valuable target for immunotherapy research." (PMID 39934467, 2025).